PGR (progesterone receptor)
Diseases named in the same sentence as PGR in open-access papers (continued):
Sharing a sentence is not in itself a finding about the gene and the disease.
breast cancer (continued). "In this study, we describe the effects of increases in ecDNA oxidation and ecDNA concentrations on various characteristics of oestrogen (ER) and progesterone receptor (PR) positive breast carcinoma cell MCF-7." (PMID 24147001, 2013). "The expression patterns of the clinically most critical molecules for breast cancer are ER, as well as progesterone receptor (PgR) and Neu/ErbB-2/ HER2." (PMID 22754462, 2012). "The main prognostic variables in early breast cancer are tumor size, grade, estrogen and progesterone receptor (ER/PgR) status, number of positive nodes and human epidermal growth factor receptor 2 (HER2) status." (PMID 23146280, 2012). "Breast cancer incidence had been significantly lower in Japan compared to America and European countries and the rates of ER/PgR-positive breast cancers from Japanese patients were also lower, especially in postmenopausal women." (PMID 22711317, 2012). "Endocrine therapy was proposed as a treatment for breast cancer in patients who were with estrogen and/or progesterone receptor-positive tumors." (PMID 22203880, 2012). "Selective progesterone receptor modulators (SPRM) are partial progesterone antagonists used for the treatment of breast cancer and uterine leiomyoma." (PMID 22272226, 2012). "In breast cancer patients with positive estrogen and/or progesterone receptor status of their primary tumors (n=10), the FSMW captured ≥5 CTC in 70% (n=7) of the cases." (PMID 22825490, 2012). "The association of estrogen receptor, progesterone receptor, and human epidermal growth factor receptor 2 (HER2) status of breast cancer patients has been extensively investigated using several approaches." (PMID 22754462, 2012). "Promoter methylation of UCHL1 is significantly correlated with pathologic stage of breast cancer and progesterone receptor status." (PMID 22279545, 2012). "From breast cancer studies, it is well established that progesterone receptor (PgR) expression in cells with estrogen receptors (ER) depends on estrogen exposure during previous days." (PMID 22870942, 2012). "Her-2 (ErbB-2), Estrogen Receptor (ER) and Progesterone Receptor (PR) are the most commonly used biomarkers and therapeutic targets in breast cancer patients." (PMID 22957061, 2012). "The main prognostic variables in early breast cancer are tumor size, histological grade, estrogen receptor/progesterone receptor (ER/PgR) status, number of positive nodes and human epidermal growth factor receptor 2 (HER2) status." (PMID 23146280, 2012). "Several clinicopathological variables are routinely examined with a breast cancer diagnosis, including estrogen receptor (ER), progesterone receptor (PR), HER2/neu amplification, lymph node involvement and histopathological grade." (PMID 22375924, 2012). "At least 75% of breast cancers express estrogen receptor α (ER) and/or progesterone receptor (PR), which are tumor biomarkers of estrogen dependence." (PMID 23087906, 2012). "In further studies we are going to analyse the exact function of SERBP1 in the development of breast cancer and its interaction with the progesterone receptor and PAI-1 in this context." (PMID 23236990, 2012). "In this retrospective study, we sought to establish the role of toremifene as an endocrine therapy for premenopausal patients with estrogen and/or progesterone receptor positive breast cancer besides tamoxifen." (PMID 22548922, 2012). "By analogy with these findings, very recently, fulvestrant treatment was reported to down-regulate the progesterone receptor levels, monitored by PET in STAT1-deficient mammary tumors in mice, reflecting the response to endocrine therapy." (PMID 23236424, 2012). "As much as 81% of male breast cancers express the progesterone receptor, and even 90% of them express the estrogen receptor." (PMID 23273269, 2012).
breast cancer (continued). "Triple-negative (TN) breast cancer describes a subgroup of tumours that lack expression of oestrogen receptor (ER), progesterone receptor (PR) and human epidermal growth factor receptor (HER2)." (PMID 22333603, 2012). "Estrogen receptor/progesterone receptor (ER/PR) expressing breast cancers are treated with endocrine therapy." (PMID 23961352, 2012). "We illustrate the functionality of Cutoff Finder by the analysis of the gene expression of estrogen receptor (ER) and progesterone receptor (PgR) in breast cancer tissues." (PMID 23251644, 2012). "In fact, most patients (85.5%) had ER or PgR-positive (≥1%) breast cancer, while only 14.5% had both ER and PgR 0%." (PMID 22672524, 2012). "The MCF7 cell line, which express E-cadherin, estrogen receptor and progesterone receptor, is considered as a good model to mimic luminal breast cancer." (PMID 23056409, 2012). "Most participants had Stage I or II breast cancer with an estrogen and progesterone receptor positive tumor." (PMID 23316388, 2012). "Cell line models of HER2-positive breast cancer that had acquired resistance to lapatinib or to lapatinib plus trastuzumab showed increased expression of ER or a downstream target of ER (progesterone receptor, IGF-IR, Cav-1)." (PMID 23227361, 2012). "Estrogen receptor-alpha-positive (ERα+) and progesterone receptor-positive (PR+) breast cancer account for approximately 60% to 70% of the breast cancer cases diagnosed in humans." (PMID 22264274, 2012). "As the majority (80%) of MNU-induced mammary carcinomas are hormone-dependent resveratrol appears to increase the ER - and/or PgR-positive cells presumed to be the progenitors of hormone-dependent carcinomas resulting in a higher mammary carcinoma yield." (PMID 22507225, 2012). "It is important to note that our MDA-231 orthotopic breast carcinoma models used for these studies are triple negative for ERα/PgR/HER2." (PMID 23029096, 2012). "In a randomised, double-blind study in PMW (N=337) with ER+ and/or PgR+ breast cancer comparing letrozole with tamoxifen, letrozole was superior to tamoxifen in overall objective response rate (55 vs 36% P<0.001)." (PMID 21364577, 2011). "Triple-negative breast cancer (TNBC), which is characterized by negativity for estrogen receptor, progesterone receptor and human epidermal growth factor receptor 2 (HER2), is a high risk breast cancer that lacks specific targets for treatment selection." (PMID 22126395, 2011). "In PMW undergoing primary treatment for locally advanced ER+/PgR+ breast cancer, letrozole suppressed pretreatment tumour levels of estradiol (E2), estrone (E1), and estrone sulfate (E1S) by 97.6, 90.7, and 90.1%, respectively." (PMID 21364577, 2011). "Validation of estrogen and progesterone receptor tests at local laboratories, with rigorous quality control measures, is strongly recommended in order to avoid erroneous treatment of breast cancer patients." (PMID 21971899, 2011). "Brain metastases have been found to be associated with HR-negative and triple-negative (ER-, PgR-, HER2-) breast cancers, EGFR expression, low Bcl-2, and breast cancer HER2 expression and presence of HER2 amplification." (PMID 21914172, 2011). "In multivariate analyses only early stage and progesterone receptor positvity were statistically significant related to improved overall survival in male breast cancer." (PMID 21816051, 2011). "In another double-blind study of PMW with ER+ and/or PgR+ breast cancer ineligible for BCS, patients were randomly assigned to receive either 4 months of neoadjuvant letrozole or tamoxifen." (PMID 21364577, 2011). "Approximately 23% of aggressive breast cancers contain elevated LIP and this increase in LIP is associated with reduced estrogen and progesterone receptor expression and an otherwise poor prognosis." (PMID 21854628, 2011). "One study reported higher serum levels of miR-155 in patients with progesterone receptor-positive (PR+) breast cancer compared with patients with PR- breast cancer." (PMID 21914171, 2011).
breast cancer (continued). "We demonstrate that individual CD44 isoforms can be associated to different breast cancer subtypes and clinical markers such as HER2, ER and PgR, which suggests involvement of CD44 splice variants in specific oncogenic signaling pathways." (PMID 21957977, 2011). "The evaluation of estrogen receptor (ER) and progesterone receptor (PR) expression status in breast cancer is critical because clinical and biological heterogeneity is associated with these hormone receptors." (PMID 21450081, 2011). "Steroid hormone receptors such as ER and PgR in concert with the HER2 still remain critical determinants of breast cancer subtypes and the treatment decision in daily clinical practice." (PMID 22933934, 2011). "In breast cancer, ER/PgR, HER2, and Ki-67 are important biological markers for predicting prognosis and making effective treatment decisions." (PMID 22004841, 2011). "In this setting, miRNA expression has correlated with specific breast cancer biopathologic features, such as estrogen receptor (ER) and progesterone receptor (PR) expression, tumor stage, vascular invasion or proliferation index." (PMID 21375733, 2011). "Breast cancers that gave rise first to liver metastases frequently expressed ER (52.1%), PgR (37.5%), or HER2 (33.3%)." (PMID 21914172, 2011). "We have previously identified that introducing progesterone receptor (PR) into hormone-independent breast cancer cells significantly suppressed their proliferative and invasive activities upon progesterone treatment." (PMID 22164169, 2011). "Seventy to 80% of all breast cancers are positive for estrogene (ER) or progesterone receptors (PgR)." (PMID 22933934, 2011). "Approximately 70% of breast cancers are estrogen receptor α-positive (ERα+) and progesterone receptor-positive (PR+)." (PMID 21679465, 2011). "Although many proteins have been studied as prognostic and predictive factors in breast cancer, only three alter current practice: estrogen receptor (ER), progesterone receptor (PR) and HER2." (PMID 21906370, 2011). "Currently, breast cancer is divided into major subgroups based on the combined expression of the oestrogen receptor (ER), progesterone receptor (PR) and human epidermal growth factor receptor 2 (HER2)." (PMID 22067903, 2011). "CLU expression levels correlated with tumor size, estrogen and progesterone receptor expression levels, and lymph node metastasis in breast carcinoma." (PMID 22185350, 2011). "Here we investigated the possibility that the 4ICD coactivator regulates PgR expression thereby providing a mechanistic explanation for their partially overlapping activities in breast cancer." (PMID 20550710, 2010). "Approximately 75% of primary breast cancers express ER, and more than half of these cancers also express PgR." (PMID 29147190, 2010). "It marker to evaluate cell proliferation and prognosis when combined with other breast cancer markers, such as estrogen receptor, progesterone receptor and ERBB2." (PMID 20158880, 2010). "The relative amounts of GPC and PCho in human tissue samples from triple negative and ER+/PgR+ subtypes of breast cancer corresponded well with the data from the xenografts." (PMID 20716336, 2010). "Another steroid receptor that has gained special attention in the last years of research on breast cancer is the progesterone receptor (PR)." (PMID 20520761, 2010). "The HER4 intracellular domain (4ICD) is a potent estrogen receptor (ERα) coactivator with activities in breast cancer and the developing mammary gland that appear to overlap with progesterone receptor (PgR)." (PMID 20550710, 2010). "Basic and clinical studies have shown the critical importance of the steroid receptor estrogen receptor (ER) and progesterone receptor (PR) in the development of the normal mammary gland and in the development and progression of breast cancer." (PMID 20569503, 2010).
breast cancer (continued). "Levels of each HIF-1α variant mRNA were determined in tumour samples from 53 patients with breast cancer and were compared with lymph node status, tumour size, tumour grade, peritumoural vascular invasion, OR and PgR status." (PMID 20624301, 2010). "In two cohorts of primary breast cancers, PKCα levels correlated to estrogen and progesterone receptor negativity, tumor grade, and proliferative activity, whereas PKCδ and PKCε did not correlate to clinicopathological parameters." (PMID 20398285, 2010). "Breast cancers that are positive for estrogen receptor and/or progesterone receptor respond better to endocrine therapy compared to receptor negative breast cancers." (PMID 20205715, 2010). "In order to evaluate if the choline metabolism in the xenograft models is representative for basal-like and luminal-like breast cancer in humans, they were compared to data from triple negative and ER+/PgR+ breast cancer patients." (PMID 20716336, 2010). "Accurate assessment of estrogen receptor (ER), progesterone receptor (PR), and Ki-67 is essential in the histopathologic diagnostics of breast cancer." (PMID 20663194, 2010). "We found that the autotaxin transcript levels in primary tumors of breast cancer patients was an independent factor from the tumor size, grade, metastasis, node, ER and PgR status." (PMID 20305819, 2010). "The results were similar in breast cancer stratified by hormone receptor (oestrogen receptor/progesterone receptor) status." (PMID 20051955, 2010). "The prognosis and management of breast cancer is influenced by the status of oestrogen receptor (ER), progesterone receptor (PR), and human epidermal growth factor receptor 2 (HER2) of the tumour." (PMID 20551954, 2010). "The metabolite profiles from xenografts were compared with profiles from human breast cancer, sampled from patients with estrogen/progesterone receptor positive (ER+/PgR+) or triple negative (ER-/PgR-/HER2-) breast cancer." (PMID 20716336, 2010). "Elegant studies on T47D and MCF-7 breast cancer cell lines with PNA-peptide conjugates targeting human progesterone receptor gene isoforms A and B revealed the extent to which expression of progesterone receptor protein was attenuated." (PMID 21029412, 2010). "Evaluation of metabolite levels through relative peak areas demonstrated that the mean GPC/PCho ratio was significantly higher in triple negative breast cancer than in ER+/PgR+ breast cancer." (PMID 20716336, 2010). "Tamoxifen, a selective estrogen receptor modulator, is the standard of care for premenopausal women with estrogen or progesterone receptor-positive breast cancer and a valid option for treating post-menopausal women." (PMID 20877451, 2010). "To determine if 4ICD coactivates PgR expression in breast carcinomas we quantitated the levels of PgR expression in 196 therapy naive PgR positive breast tumors using the AQUA IHC procedure." (PMID 20550710, 2010). "Luminal A and luminal B breast cancers express the oestrogen receptor (ER) and are also frequently progesterone receptor (PR) positive." (PMID 19773756, 2009). "In breast cancer models, progesterone induces c-Myc expression via a progesterone receptor regulatory element upstream of c-myc." (PMID 19785743, 2009). "Our data demonstrate that a biology-based breast cancer classification using estrogen receptor (ER), progesterone receptor (PgR), and HER2 bears independent predictive and prognostic potential." (PMID 19758440, 2009). "In summary, our results demonstrate that a breast cancer classification, simply based on the expression of the standard markers ER, PgR, and HER2 bears independent predictive and prognostic potential." (PMID 19758440, 2009). "We were not able to better delineate an immunohistochemical definition of basal type of breast cancer by adding vimentin to the immunopanel consisted of ER, PgR, HER2, CK5/6, 14 and 17 markers, when overall survival was a primary end-point." (PMID 19695088, 2009).
breast cancer (continued). "A progesterone-like growth inhibitory action of mifepristone was also shown in estrogen-resistant, progesterone receptor expressing T47Dco breast cancer cells." (PMID 19222856, 2009). "New, third-generation aromatase inhibitors (AIs) have proven comparable or superior to the anti-estrogen tamoxifen for treatment of estrogen receptor (ER) and/or progesterone receptor (PR) positive breast cancer." (PMID 19531212, 2009). "The finding that the progesterone receptor is down regulated in AAM relative to CAM samples is very intriguing in light of the fact that decreased progesterone receptor expression contributes to poor prognosis for breast cancer in African American women." (PMID 19208208, 2009). "We found that among women not using HRT, obese compared with normal weight women more often had large and progesterone receptor-positive tumours, but similar breast cancer-specific survival." (PMID 19367278, 2009). "In node-positive patients, TNBC breast carcinoma tended to demonstrate the worst 5-year overall survival by log-rank analysis, and ER-positive and/or PgR-positive and HER2-negative patients had the best 5-year overall survival (p < 0.0001)." (PMID 19534825, 2009). "The majority of carcinomas of the breast are estrogen receptor positive (estimated at 75%), progesterone receptor positive (estimated at 55%), and HER2 receptor is over-expressed (reported to be up to 25%)." (PMID 19126225, 2009). "A total of 42 cases of male breast carcinoma were examined retrospectively using immunostains for estrogen receptor (ER), progesterone receptor (PR), cytokeratin 5/6 (CK5/6), EGFR, and NF-κB." (PMID 19442295, 2009). "To more systematically study the biological significance of the results, we looked at the publications of the top informative genes (top two genes in each pathway) with keywords, like breast cancer, estrogen receptor, and progesterone receptor, of interest." (PMID 18254968, 2008). "A similar observation has already been reported in breast cancer cells, where the up-regulation of breast cancer resistance protein expression induced by the combination of E2 plus progesterone is abolished by the progesterone receptor antagonist RU486." (PMID 18541028, 2008). "As 31% of TNBCs were positive for EGFR protein in this series, we measured EGFR gene copy number in 63 TNBCs compared with 42 ER and/or PgR-positive but HER2-negative consecutive breast cancers, (which are also termed luminal subtype)." (PMID 18950515, 2008). "Among the 51 823 postmenopausal women in the Swedish Mammography Cohort, we investigated breast cancer risk in relation to the FFQ-based estimated lignan intake by oestrogen receptor (ER) and progesterone receptor (PR) subtypes." (PMID 18212757, 2008). "Triple-negative breast cancer (estrogen receptor-, progesterone receptor-, and HER2-negative) (TNBC) is a high risk breast cancer that lacks specific therapy targeting these proteins." (PMID 18950515, 2008). "Oxidative stress can modify estrogen receptor (ER) structure and function, including induction of progesterone receptor (PR), altering the biology and clinical behavior of endocrine responsive (ER-positive) breast cancer." (PMID 18631401, 2008). "The aim of this study was to assess the frequency of ERα, ERβ, PgR (progesterone receptor) and HER-2 expression in breast cancer patients with mutated BRCA1 gene and in the control group." (PMID 18405391, 2008). "American Society of Clinical Oncology guidelines recommend that an AI be included in a woman's adjuvant regimen if she has ER-positive and/or PgR-positive breast cancer." (PMID 17892469, 2007). "Breast cancer patients with tumors that are estrogen receptor (ER)-positive and/or progesterone receptor (PR)-positive have lower risks of mortality after their diagnosis compared to women with ER- and/or PR-negative disease." (PMID 17239243, 2007).